TAGLN (transgelin)
Diseases named in the same sentence as TAGLN in open-access papers (continued):
Sharing a sentence is not in itself a finding about the gene and the disease.
TAGLN also shares sentences with these, for which no sentence is quoted: abdominal aortic aneurysm (3 papers); congenital heart disease (3); fibrosis (3); liver fibrosis (3); aortic aneurysm (2); colon (2); colon adenocarcinoma (2); dyslipidemia (2); glomerular disease (2); head and neck squamous cell carcinoma (2); hyperlipidemia (2); ischemic stroke (2); lymphoma (2); pulmonary hypertension (2); anterior diaphragmatic hernia (1); Aortic dissection (1); arterial diseases (1); arteriovenous malformations (1); astrocytoma (1); bipolar disorder (1); breast adenocarcinoma (1); campomelic dysplasia (1); cardiac arrhythmia (1); Cerebral ischemia (1); childhood onset asthma (1); colonic polyp (1); Connective Tissue Disease (1); dilatation (1); dissection (1); erectile dysfunction (1).
A further 30 diseases each share a sentence with TAGLN in 1 paper.